Y_RNA (Y RNA )
Gene: Miscellaneous RNA gene on chromosome 2 (152,284,350 to 152,284,460, reverse strand). Ensembl gene ENSG00000199884.
Homologues: Orthologues: chimpanzee Y_RNA (99% identical). Paralogues in human: RNY1 (89% identical), Y_RNA (88% identical), Y_RNA (86% identical), Y_RNA (85% identical), RNY1P11 (84% identical), Y_RNA (84% identical), RNY1P8 (83% identical), Y_RNA (83% identical), RNY1P5 (82% identical), Y_RNA (82% identical), RNY1P10 (81% identical), Y_RNA (81% identical), and 96 more.